RNU6-255P (RNA, U6 small nuclear 255, pseudogene)
Gene: Small nuclear RNA gene on chromosome Y (19,018,983 to 19,019,087, reverse strand). Ensembl gene ENSG00000252766.
Homologues: Orthologues: chimpanzee U6 (98% identical), rabbit U6 (85% identical), guinea pig U6 (82% identical), rabbit U6 (79% identical), guinea pig U6 (77% identical). Paralogues in human: RNU6-944P (88% identical), RNU6-1094P (87% identical), RNU6-1243P (87% identical), RNU6-43P (86% identical), RNU6-454P (86% identical), RNU6-727P (86% identical), RNU6-1309P (85% identical), RNU6-130P (85% identical), RNU6-879P (85% identical), RNU6-961P (85% identical), RNU6-1286P (84% identical), RNU6-1331P (84% identical), and 1287 more.